IL1B (interleukin 1 beta)
Diseases named in the same sentence as IL1B in open-access papers (continued):
Sharing a sentence is not in itself a finding about the gene and the disease.
acne (95 papers, 2013 to 2025). An inflammatory process of the sebaceous glands which is characterized by comedones, nodules, papules and/or pustules on the skin. "Elevated levels of IL-1β are linked to a variety of skin pathologies such as psoriasis, acne vulgaris, and cutaneous lupus erythematosus." (PMID 38396697, 2024). "The activation of the NLRP3 inflammasome promotes the maturation of caspase-1 and triggers the release of the downstream acne-pathogenic cytokines IL-1β and IL-18, which subsequently activates the secondary inflammatory mediators, including IL-6 and IL-832." (PMID 38062074, 2023). "Among the multiple subtypes of family proteins, NLRP3 has been associated with acne; C. acnes activates this inflammasome inducing IL-1β production in a caspase-1 dependent manner involving potassium efflux." (PMID 35910763, 2022). "Dimerization of TLR1 is a key process in the activation of the inflammasome in the pilosebaceous follicle in acne, which will cause the secretion of IL-1β." (PMID 35889022, 2022). "The same increased IL1β production was also observed when porphyrin extracts of acne-associated P. acnes were used." (PMID 36439142, 2022). "The ability of P. acnes to activate TLR2 signaling in myeloid cells, especially macrophages, has been already demonstrated in acne vulgaris confirming another route of P. acnes-associated IL-1β production." (PMID 30155445, 2018). "A number of proinflammatory cytokines, including interleukin-6 (IL-6), tumor necrosis factor-α (TNF-α), and interleukin-1β (IL-1β), have been implicated in the inflammatory process of acne." (PMID 24078775, 2013). "Based on these results, we selected compounds and evaluated whether compounds were able to inhibit the expression of NLRP3, IL-1β, 5α -R1 associated acne." (PMID 36624865, 2022). "Notably, both porphyrin production and IL-1β release are higher in acne-associated strains." (PMID 37344849, 2023). "Zn deficiency exacerbates acne-related inflammation, as evidenced by elevated IL-1β levels in an acne-like mouse model." (PMID 40507073, 2025). "In acne treatment, the production of IL-6 is regulated by IL-1β and TNF-α, which further amplifies the inflammatory cascade." (PMID 39942620, 2025). "This enzyme mediates the inflammatory response by producing pro-inflammatory cytokines, such as IL-1β and IL-18, which contribute to the development of acne vulgaris." (PMID 41178942, 2025). "In acne pathogenesis, the upregulation of Th17-related cytokines such as IL-8, IL-1β, IL-6 and TGF-β is well documented." (PMID 40668089, 2025). "Borneol also effectively treats acne because of its anti-inflammatory and analgesic effects, and was found to inhibit acne-mediated production of IL-6, IL-1β, interleukin-8 (IL-8) and TNF-α by inhibiting the NFκB activation pathway." (PMID 41573729, 2025). "For instance, a study by Li and colleagues showed that ADSCs diminished IL-1β secretion by restricting mitochondrial ROS production, which further obstructed the NLRP3 inflammasome and alleviated inflammation linked to acne." (PMID 40422225, 2025). "The Toll-like receptor (TLR)/NF-κB pathway, activated by C. acnes and other stimuli, mediates the release of pro-inflammatory cytokines such as IL-1β, a key driver of acne inflammation." (PMID 41463630, 2025). "The ability of CBD to counteract the C. acnes-induced inflammatory response by downregulating cytokines like CXCL8, IL-1α, and IL-1β further positions it as an anti-inflammatory agent for acne." (PMID 38904694, 2024). "In acne, all patients with inflammatory acne have dermal and epidermal IL-1β expression, and the expression level correlates with disease severity." (PMID 38321132, 2024). "Previous studies have indicated that IL-1β plays a crucial role in the development of inflammation in rosacea and acne." (PMID 38321132, 2024). "substantiated that kinofen has the potential to inhibit NLRP3 inflammasome activation and reduce IL-1β expression, suggesting its applicability in treating acne vulgaris." (PMID 38550588, 2024).
acne (continued). "As a result, agents that act suppressing the ROS, IL‐1β and IL‐6 productions have been widely used for acne treatment." (PMID 38426932, 2024). "It should be emphasized that IL-1β is a crucial cytokine in AV pathogenesis, severity, and post-acne scar formation." (PMID 39744637, 2024). "We next investigated the effects of RPE and PPH on the induction of key proinflammatory cytokines during the acne pathogenesis (IL‐1β and IL‐6) in LPS‐stimulated RAW 264.7 cells." (PMID 38426932, 2024). "L. rhamnosus significantly improved acne-like symptoms in rats by suppressing the level of inflammatory cytokines such as IL-1β, IL-6, and TNF-α." (PMID 38250060, 2023). "In acne lesions, C. acnes invasion stimulates sebaceous gland activity, resulting in excessive sebum secretion and the release of IL-6, IL-1β, IL-8, TNF-α8." (PMID 38062074, 2023). "This response is evident as C. acnes induces the activation of monocyte-macrophage NLRP3-inflammasome and boosts the secretion of IL-1β in acne, thereby demonstrating its role in skin inflammation." (PMID 37344849, 2023). "Sebocytes also promote T cell differentiation into Th17 cells, via IL-6, TGF-β and IL-1β production that are released during acne development." (PMID 35910763, 2022). "In particular, the concentration of IL-1β in serum decreased, and the area of acne lesions, decreased from the histological analysis." (PMID 35269651, 2022). "Previous evidence demonstrated that IL-1β promotes the inflammatory response of P. acnes in vitro and in vivo, and IL-8 is also an essential pro-inflammatory cytokine in the pathogenesis of acne." (PMID 36120319, 2022). "All these genes encode proinflammatory cytokines and chemokines previously detected in acne lesions and are linked to activation of the NF-κB pathway, inducing the upregulation of TNF-α, CXCL8/IL-8, IL-1β, CXCL1 and CXCL2." (PMID 35563458, 2022). "In acne inflammation pathogenesis, C. acnes plays an important trigger role through IL-6 and IL-8 secretion by follicular keratinocytes and IL-1β, TNF-α, IL-8 and IL-12 by monocytes." (PMID 36145700, 2022). "NF-κB increases the expression of pro-inflammatory factors including interleukin 1β (IL-1β), IL-6 and tumor necrosis factor alpha, three of which are essential in acne pathology." (PMID 35211023, 2022). "Typical cytokines from neutrophils, macrophages, and epithelial cells, such as TNF-α and IL-1β, are elevated in acne lesions." (PMID 35740016, 2022). "TNF-α, IL-6 and IL-1β are inflammatory molecules involved in both acute and chronic inflammatory acne." (PMID 36145700, 2022). "We found that meclozine decreased the in vitro production of CXCL8/IL-8 and IL-1β mRNA and protein in a dose-dependent manner; CXCL8/IL-8 and IL-1β are known to be involved in acne development." (PMID 35625668, 2022). "Studies suggest that C. acnes can activate the NLRP3 inflammasome pathway, eventually resulting in elevated IL-1β levels and contributing to the pathogenesis of acne." (PMID 33849530, 2021). "In the previous study, researchers have identified that caspase-1, ASC, and NLRP3 knockdown or knockout inhibits P. acnes-induced IL-1β production in acne." (PMID 34603464, 2021). "The most refractory complication of acne is scar formation, which involves the production of pro-inflammatory cytokines such as IL-1α, IL-1β, IL-6, TNF-α, and TGF-β54." (PMID 32765835, 2020). "Nitrate oxide can be an alternative treatment for acne in humans by reducing IL-1β, IL-8, TNF-α, and IL-6 induced by monocytes and IL-8 and IL-6 induced by keratinocytes via innate immunity." (PMID 32765835, 2020). "Acne lesions have high levels of IL-1β, which is thought to be a crucial driver of the inflammatory response in acne vulgaris, and is initiated by the activation of the NLRP3 inflammasome." (PMID 33111746, 2020). "Among cytokines, IL-15 was decreased in the DTCV acne group, while IL-1β was increased in the female subjects in the other PI groups compared with the control group." (PMID 31951642, 2020).
acne (continued). "IL-1β is abundantly expressed in inflammatory acne lesions, and increased production of IL-12 has been detected following exposure to heat-killed P. acnes." (PMID 30987239, 2019). "Of particular note is the observation that P. acnes can activate the NOD-like receptor protein 3 (NLRP3)-inflammasome and the protease Caspase 1 of monocytes/macrophages and sebocytes, resulting in the production of IL-1β which is abundant in acne lesions." (PMID 31086023, 2019). "It contributes to the inflammatory response of acne by stimulating the production of inflammatory cytokines like IL-8, IL-1β and TNF-α from keratinocytes, sebocytes, and inflammatory cells." (PMID 31252651, 2019). "As with acne vulgaris, IL-1β appears to play a key role in disc degeneration, including matrix destruction, angiogenesis and cellular apoptosis and senescence." (PMID 30155445, 2018). "The fact that IL-1β is secreted in acne skin condition has proposed valuable effects of IL-1β-targeted therapy in patients suffering from anti-inflammatory acne-lesions." (PMID 30261862, 2018). "As an exemplar of this approach, treatment of patients with acne using the humanized anti-IL-1β antibody Gevokizumab demonstrated significant clinical response with reductions in inflammatory lesions." (PMID 30155445, 2018). "Lesions from these and other skin diseases tended to show elevated expression of IL-1B/IL-36-increased DEGs and decreased expression of IL-1B/IL-36-decreased DEGs (e.g., acne, eschars, and H. ducreyi infection)." (PMID 29434599, 2018). "During acne inflammatory reaction, P. acnes induces the production of pro-inflammatory cytokines such as interleukin (IL)-1β, IL-6, IL-8, and tumor necrosis factor (TNF)-α in monocytes and keratinocytes." (PMID 30261862, 2018). "The induction of IL-1β is believed to be a key driver of inflammatory responses in acne and is mediated via inflammasome activation." (PMID 30155445, 2018). "Our results are in line with the prior observations concerning up-regulated TNF-α and IL-1β in acne lesions examined by RT-PCR." (PMID 25153527, 2014). "These two cytokines (TNF-α and IL-1β) propagate the acne inflammatory response by acting on endothelial cells to elaborate adhesion molecules to facilitate recruitment of inflammatory cells into the skin." (PMID 24078775, 2013). "First, we identified loops in promoter capture Hi-C (pc Hi-C) in keratinocytes encompassing the acne-associated variants, highlighting that both variants interact with the promoter region of IL1A, with rs2708914 also connected to IL1B, complementing the eQTL results." (PMID 39975900, 2025). "The Zn-de-Model group exhibited higher levels of these cytokines than the Model group, with increases of 51.74% for TNF-α, 11.91% for IL-1β, 118.06% for IL-17A, 19.64% for MMP9, and 17.05% for CXCL1/KC, indicating that Zn deficiency leads to more severe skin inflammation in acne-like mice." (PMID 40507073, 2025). "While these cytokines induce naïve T cells to differentiate into effector Th17 cells in acne, IL-6 and IL-1β production may also activate ILC3s and enhance their effector function." (PMID 38396697, 2024). "IL-1β plays a pivotal role in the initiation of acne inflammation." (PMID 38736879, 2024). "Since the conversion of ILC3s and ILC2s into ILC1s requires inflammatory cytokines such as IL-12 and IL-1β, it remains likely that pathogenic strains of C. acnes may impact this conversion by changing the cytokine milieu within the PSU in acne." (PMID 38396697, 2024). "IL-1β mRNA and IL-1β are abundant in inflammatory acne lesions." (PMID 38792208, 2024). "IL-1R can be activated by IL-1α and IL-1β within the inflamed comedones of acne patients." (PMID 38731983, 2024). "It has recently been shown that the active form of IL-1β is prevalent in inflamed acne lesions." (PMID 38249466, 2023). "Even in acne, 1,8-Cineol-containing leaf extracts suppress the expression of IL-1β and IL-6." (PMID 37570874, 2023).
acne (continued). "Moreover, we found that PDTC improved C. acnes-induced inflammation by attenuating C. acnes-induced IL-1β secretion in a mouse acne model." (PMID 36901873, 2023). "IL-1β is contributed to the development of inflammatory papules, pustules, and nodules in acne." (PMID 35269651, 2022). "It is speculated that the acne-associated inflammation can in turn alter clock gene expression via the inflammatory cytokines such as TNF-α and IL-1β 29,30." (PMID 35414779, 2022). "Thus, cytokines orchestrating the immune response in acne includes Interleukin 1β (IL-1β), Interleukin 6 (IL-6), Interleukin 8 (IL-8), and Tumor Necrosis Factor alpha (TNFα) involved in the inflammatory pathogenesis." (PMID 35910763, 2022). "P. acnes-induced IL1β activation in SG may have a role in combating skin infections and in acne pathogenesis." (PMID 36439142, 2022). "Among them, IL-1β is known to show high content in serum in people with acne." (PMID 35269651, 2022). "In light of the potential role of IL-1β in acne pathogenesis, monoclonal anti-IL-1β and/or molecules that could regulate NLRP3, caspase-1, or K+ efflux should be considered in treatments of acne." (PMID 35329904, 2022). "Since NLRP3 is the first mediator in the activation of the inflammasome pathway, inhibition of NLRP3 expression may inhibit the next step of the pathway, in which caspase-1 finally activates IL-1β, resulting in the development of acne." (PMID 36624865, 2022). "IL-1β plays an important role in pathogenesis of acne vulgaris." (PMID 35329904, 2022). "C. acnes CAMP factor 2 is considered to be a virulence factor because it can induce inflammation in vivo and has been used as an antigen to elicit monoclonal antibodies, decreasing the production of CXCL8/IL-8 and IL-1β in ex vivo skin explants from patients with acne." (PMID 35563458, 2022). "For these reasons, many studies have noted IL-1β as a novel potential therapeutic target in acne." (PMID 35269651, 2022). "IL-1β expression is upregulated in the sebaceous glands of acne lesions." (PMID 33534121, 2021). "A key component of inflammatory responses to P. acnes in acne appears to be interleukin (IL)-1β." (PMID 30155445, 2018). "Besides IL-6, we also found that TNF-α and IL-1β were increased following PA treatment, which are also critically important in acne inflammation." (PMID 24078775, 2013). "Another study has shown that in addition to inhibiting the synthesis of IL-1β and other pro-inflammatory factors, IL-10 can also promote the production of tissue inhibitors of matrix metalloproteinases (TIMPs), thereby inhibiting the expression of MMPs and reducing scar formation in acne." (PMID 40520168, 2025). "Hence, targeting the NLRP3 inflammasome and IL-1β could be a potential therapeutic approach for acne." (PMID 39421673, 2024). "In contrast, the sebum of acne patients contains elevated levels of PA, which may also play a role in the pathogenesis of acne by enhancing the secretion of interleukin (IL)-1β in in vitro differentiated monocyte-derived macrophages and the production of IL-6 and IL-8 by human sebocytes." (PMID 37571253, 2023). "Therefore, we consider that the IL-1β-IL-1R signaling pathway may emerge as a key player in the developmental mechanism of severe acne." (PMID 37554505, 2023). "Inhibiting NLRP3 and IL-1β expression may reverse or prevent acne." (PMID 36624865, 2022). "Inhibiting NLRP3 and IL-1β expression may also reverse or prevent acne." (PMID 36624865, 2022). "The finding that SAA has also been identified as a danger signal that triggers activation and IL-1β secretion, a key cytokine in acne pathogenesis, sets altogether the basis for intriguing speculations on sebocyte derived SAA to be tested as a possible therapeutic target." (PMID 29927962, 2018). "Therefore, IL-1β is thought to play an important role in acne pathogenesis." (PMID 28588486, 2017).
acne (continued). "Interestingly, PAPA syndrome (pyogenic sterile arthritis, pyoderma gangrenosum and acne) caused by mutations in the cytoskeletal adapter PSTPIP1 (which binds to WASp) shares cytoskeletal features with WAS and is also associated with overt IL-1β production." (PMID 29146903, 2017). "Tanshinone can reduce the levels of IL-8, IL-6, IL-1β, and TNF-α in acne model rats, as profiled by lipidomics, with the mechanism possibly related to sphingolipid and glycerophospholipid metabolism pathways." (PMID 40230697, 2025). "During acne pathogenesis, sebocytes and monocytes/macrophages can activate NLRP3 inflammasomes and release IL-1β." (PMID 41307843, 2025). "AzA’s anti-inflammatory activity is mediated through the downregulation of pro-inflammatory cytokines, including interleukin-1 beta (IL-1β) and tumor necrosis factor-alpha (TNF-α), which are key drivers of inflammation in acne and rosacea pathophysiology." (PMID 41011144, 2025). "CPT contributes to reducing the levels of inflammatory cytokines IL-1β, IL-6, IL-8, and TNF-α in acne model rats." (PMID 40230697, 2025). "It acts against the main factors contributing to the pathogenesis of acne by inhibiting pro-inflammatory mediators (e.g., COX-2, PGE2, IL-1β and TNF-α)." (PMID 39596008, 2024). "In parallel investigations, CBD treatment at 10 μM within an LPS-induced acne-like context exhibited decreased levels of TNF-α, IL-1β, and IL-6." (PMID 38904694, 2024). "Inflammation and cytokines, such as IL-1β, TNF-α, and IL-17, play pivotal roles in acne inflammation, underscoring the importance of regulating these cytokines as potential targets for acne treatments to mitigate inflammation and lesion formation." (PMID 38646359, 2024). "The presence of IL-17A-positive T cells and Th17-related cytokines (IL-1β, IL-6, TGF-β, IL23p19) is also characteristic of acne lesions." (PMID 39744637, 2024). "It was found that baicalin significantly decreased the expression of M1 macrophage-related cytokines such as IL-1β, IL-6, TNF-α and NLRP3 in acne models, and inhibited the M1 polarization of macrophages by inhibiting the nuclear translocation of NF-κB p65." (PMID 38736879, 2024). "The expression of CXCL10, MMP9, IL1B, CXCL8, and CXCR4 were co-regulated by IRF1, STAT1, STAT3, IKBKB, HDAC1, ETS1, and CEBPB, which were highly expressed in rosacea and acne lesions." (PMID 38321132, 2024). "The experimental results confirmed that GA inhibited lipid synthesis in vitro and in vivo, improved the symptoms of acne vulgaris, prevented mast cell infiltration and decreased the level of pro-inflammatory cytokines, including TNF-α, IL-1β and IL-6." (PMID 38792208, 2024). "PPAR-γ, TNF, IL-1β, IL-6, TLR and NFκB1 were identified as potential core targets of GA in the regulation of acne vulgaris." (PMID 38792208, 2024). "This resulted in the alleviation of acne symptoms and a reduction in serum levels of TNF-α and IL-1β in rats." (PMID 38550588, 2024). "In this study, we evaluated the effect of PDTC on C. acnes-induced inflammatory signaling pathways using in vitro and in vivo mouse acne models and found that PDTC ameliorates C. acnes-induced skin inflammation by inhibiting IL-1β secretion." (PMID 36901873, 2023). "To address the pathogenesis of acne vulgaris, we examined the expression of TNF-α, IL-1β in serum, and TLR2/NF-κB signaling pathway in tissues." (PMID 37159798, 2023). "Proinflammatory cytokines such as IL-1β, IL-6, IL-8, and TNF-α are responsible for the follicular keratinization and inflammation of acne." (PMID 35947554, 2022). "Several inflammatory cytokines such as TNF-α, IL-1β, COX-2 are known to be responsible for follicular hyper-keratinization and are involved in the process of changing these acne lesions." (PMID 35269651, 2022). "It is worth noting that, cytokines, i.e., IL-1β and IL-6 i TGF-β, were also found in acne lesions, and they play a significant role in the activation of Th17." (PMID 35329904, 2022).